PKIA (cAMP-dependent protein kinase inhibitor alpha)
Description:
Extremely potent competitive inhibitor of cAMP-dependent protein kinase activity, this protein interacts with the catalytic subunit of the enzyme after the cAMP-induced dissociation of its regulatory chains.
Synonyms: PRKACN1
Tractability: Small molecule: a structure with a bound ligand is known. PROTAC: its protein half-life has been measured.
Gene: Protein-coding gene on chromosome 8 (78,516,303 to 78,605,267, forward strand). Ensembl gene ENSG00000171033.
Gene Ontology:
Molecular function: cAMP-dependent protein kinase inhibitor activity; protein binding; protein kinase A catalytic subunit binding
Biological process: negative regulation of cAMP-dependent protein kinase activity; negative regulation of cAMP/PKA signal transduction
Cellular component: cytoplasm; nucleus
Genetic constraint (gnomAD): Loss-of-function variants: 1 observed, 2.97 expected, observed/expected ratio (o/e) 0.34, 90% interval 0.12 to 1.48. That is too few expected variants to judge how well the gene tolerates losing a copy. Missense variants: 24 observed, 21.7 expected, observed/expected ratio (o/e) 1.11, 90% interval 0.8 to 1.55. Synonymous variants: 4 observed, 8.2 expected, observed/expected ratio (o/e) 0.49, 90% interval 0.24 to 1.12.
Homologues: Orthologues: chimpanzee PKIA (100% identical), dog PKIA (100% identical), rabbit PKIA (100% identical), pig PKIA (99% identical), guinea pig PKIA (97% identical), mouse Pkia (97% identical), rat Pkia (97% identical), tropical clawed frog pkia (64% identical). Paralogues in human: PKIB (34% identical), PKIG (32% identical).
Diseases named in the same sentence as PKIA in open-access papers:
PKIA is named in the same sentence as 18 diseases in open-access papers, as found by Europe PMC text mining. Sharing a sentence is not in itself a finding about the gene and the disease. The quoted sentences say what the papers report.
lung carcinoma (2 papers, 2022 to 2023). "Hazard ratio(HR) > 1 represents high-risk genes, HR < 1 represents low-risk genes, and found that CFTR and PKIA genes (P < 0.05) have prognostic significance in lung cancer." (PMID 37644544, 2023). "Our study shows that the methylation status of CFTR and PKIA can be used as potential prognostic biomarkers and therapeutic targets in lung cancer, and their prognostic value needs to be further explored to improve the survival prediction of patients." (PMID 37644544, 2023). "DNA methylation is also associated with lung cancer prognosis and is essential for its growth and metastasis.In this article, we discuss the role of CFTR and PKIA methylation in lung cancer, as revealed by data analysis from TCGA and GEO." (PMID 37644544, 2023). "Our study revealed that the methylation status of CFTR and PKIA can serve as potential prognostic biomarkers and therapeutic targets in lung cancer." (PMID 37644544, 2023). "A report has suggested the role of over-expressed PKIA in the tumor growth of prostate cancer and proposed gene amplifications of PKIA across in prostate and lung cancers." (PMID 36204642, 2022). "We found that the methylation of CFTR and PKIA genes correlated with the prognosis of lung cancer." (PMID 37644544, 2023). "We identified two lung cancer-specific methylation markers, CFTR and PKIA." (PMID 37644544, 2023).
osteosarcoma (2 papers, 2022). A usually aggressive malignant bone-forming mesenchymal neoplasm, predominantly affecting adolescents and young adults. "Although osteosarcoma patients with low PKIA expression was reported to have poor prognosis, our TCGA-based expression and survival analysis results indicated a correlation between PKIA high expression and worse prognosis for HCC patients." (PMID 36204642, 2022).
prostate carcinoma (2 papers, 2022 to 2023). A carcinoma that arises from epithelial cells of the prostate gland. "PKIA is elevated in prostate cancer and associated with reduced progression-free survival, and its depletion leads to reduced tumor growth and migration, and increased susceptibility to anoikis." (PMID 37644544, 2023).
breast tumors (1 paper, 2025). "We identified 34 differentially expressed genes in metastatic breast tumors, with CCDC6, PKIA, UACA, and PFKP significantly upregulated (p < 0.05)." (PMID 40821334, 2025).
celiac disease (1 paper, 2016). An autoimmune genetic disorder with an unknown pattern of inheritance that primarily affects the digestive tract. "It has been previously reported that intestinal PKIA gene expression was increased among patients with untreated celiac disease." (PMID 27015091, 2016).
melanoma (1 paper, 2021). A malignant, usually aggressive tumor composed of atypical, neoplastic melanocytes. "Our results indicate that miR-3662 may repress melanoma cell proliferation, migration and invasion by down-regulating PKIA and ZNF831." (PMID 34616613, 2021).
Obesity (1 paper, 2015). Accumulation of substantial excess body fat. "PKIA is involved in pancreatic beta-cell function and 16p11.2 has been widely reported in the literature as contributing to the genetic risk of obesity, potentially linked to insulin signalling." (PMID 25424174, 2015).
tumor (7 papers, 2016 to 2025). "miR-210-3p levels inversely correlated with the expression of PKIA, a protein implicated in G-protein coupled Gs-cAMP signaling and deregulation of tumor growth." (PMID 39409003, 2024). "In this research, the expression levels of tumor-associated macrophages (TAMs)-related markers (CCL2, CD68 and IL10) were a positive correlated PKIA expression, indicating an ontogenetic role of PKIA in HCC." (PMID 36204642, 2022). "Given that morphological plasticity is a key determinant of cell migration, many of the identified genes were found to have a role in promotion of tumor cell migration and invasion, including ECM production and mesenchymal state induction (HEG1, BZW2, DCAF13, SQLE, PKIA)." (PMID 35879361, 2023). "Although PKIA and NR3C2 are not well understood in the context of TNBC, emerging data from other cancer types indicate they may have important roles in kinase signaling and tumor biology, necessitating further functional studies." (PMID 41017855, 2025).
cancer (2 papers, 2024 to 2025). A tumor composed of atypical neoplastic, often pleomorphic cells that invade other tissues. "The three PKI isoforms all share some specificity to bind to the PKA-c, but PKIB has the least inhibitory binding effect on PKA-c, thus the focus on PKIα in cancer studies." (PMID 38731883, 2024). "The most widely characterized concerning cancer treatment and development is PKIα." (PMID 38731883, 2024).
PKIA also shares sentences with these, for which no sentence is quoted: Anxiety (1 paper); bladder cancer (1); depression (1); glioblastoma (1); inflammation (1); lung adenocarcinoma (1); metastatic melanoma (1); psychiatric disorder (1); schizophrenia (1).